RN7SL202P (RNA, 7SL, cytoplasmic 202, pseudogene)
Gene: Miscellaneous RNA gene on chromosome 19 (3,920,245 to 3,920,506, reverse strand). Ensembl gene ENSG00000266627.
Homologues: Paralogues in human: Metazoa_SRP (82% identical), RN7SL377P (79% identical), Metazoa_SRP (79% identical), RN7SL155P (79% identical), RN7SL850P (78% identical), RN7SL48P (77% identical), Metazoa_SRP (77% identical), Metazoa_SRP (75% identical), RN7SL32P (75% identical), RN7SL356P (75% identical), RN7SL716P (74% identical), RN7SL279P (74% identical), and 706 more.